XBP1 (X-box binding protein 1)
Diseases named in the same sentence as XBP1 in open-access papers (continued):
Sharing a sentence is not in itself a finding about the gene and the disease.
Hyperglycemia (16 papers, 2012 to 2024). An increased concentration of glucose in the blood. "Previous studies have demonstrated that XBP1‐deficient mice exhibited moderate hyperglycemia and glucose intolerance, with reduced insulin secretion originating from β‐cells." (PMID 38967361, 2024). "Indeed, disruption of the XBP1 gene in pancreatic β-cells in mice using the RIP-Cre system resulted in hyperglycemia and abnormal β-cell function caused by decreased insulin secretion, decreased insulin granule content and impaired insulin processing." (PMID 25011481, 2014). "In blastocyst stage embryos, we found that the Grp78 expression was higher after in vivo DM exposure, and both pro-survival UPR markers p-Perk and Xbp1 were increased in response to hyperglycaemia in vitro and in vivo." (PMID 34140543, 2021). "These deficits are of a similar scale to those we report here after just 20 weeks of hyperglycemia in diabetic XBP1 cKO mice." (PMID 31242599, 2019). "In contrast, diabetic XBP1 cKO mice, after a 20-week hyperglycemia, demonstrate multiple deficits in retinal function and structure that are not found in diabetic WT mice and display more severe neuronal damage compared to diabetic WT mice." (PMID 31242599, 2019). "A role for XBP1 in the pancreas was demonstrated by the fact that β‐cell‐specific XBP1 mutant mice show hyperglycaemia and glucose intolerance due to decreased insulin release of β‐cells." (PMID 30027602, 2019). "However, in diabetic XBP1 cKO retinas, we found a significant approximately 12% decrease in Brn3a-positive RGCs in the GCL of diabetic XBP1 cKO mice after 20 weeks of hyperglycemia." (PMID 31242599, 2019). "Thus, after 20 weeks of hyperglycemia, diabetic XBP1 cKO mice showed retinal degeneration to a greater extent than diabetic WT mice, when compared to age-matched non-diabetic mice." (PMID 31242599, 2019). "Similarly, conditional deletion of X-box binding protein 1 (XBP1) in pancreatic β-cells induced hyperglycemia and glucose intolerance resulting from reduced insulin secretion." (PMID 26840310, 2016). "β cell-specific mice defective in XBP1 exhibit hyperglycemia and glucose intolerance due to decreased insulin secretion from their β cells, suggesting that XBP1 may be required for glucose-stimulated proinsulin processing and insulin secretion." (PMID 24705207, 2013). "However, as the ROS continues to accumulate under sustained hyperglycemia, the anti-oxidant capacity is overwhelmed and an oxidative stress occurs at day 3 to 5 when XBP1 activity is reduced." (PMID 22474421, 2012). "During times of extreme or chronic stress, for example sustained hyperglycemia, the capacity of the UPR is overwhelmed, induces the T-UPR, and drive IRE1a autophosphorylation and XBP1 mRNA splicing." (PMID 29416111, 2018). "The data showed high glucose and lipids mixture induced ER stress (PERK, CHOP, IREA, Xbp1, and ATF6), inflammation (iNOS and Cox2), and anti-angiogenic factors (Tbsp1), suggesting that in type 2 diabetes, hyperglycemia and hyperlipidemia contribute to the immune cells' dysregulation." (PMID 38094119, 2023). "We observed that while cleavage stage embryos activate Grp78/p-Perk pathway, and not the IRE1α/XBP1 pathway, in response to both in vivo and in vitro hyperglycaemia; at the blastocyst stage both pro-survival UPR transducers were found to be activated." (PMID 34140543, 2021). "After 20 weeks of hyperglycemia, retinal morphology was examined in diabetic and age-matched non-diabetic XBP1 cKO mice and WT mice." (PMID 31242599, 2019). "To ascertain the pathophysiological relevance of XBP1 for DN, we induced persistent hyperglycaemia in mice lacking XBP1 specifically in podocytes (XBP1flox/flox x PodCre)." (PMID 25754093, 2015). "Interestingly, ATF4 and CHOP, but not ATF6 and s-XBP1, were further enhanced by hyperglycemia compared to the CON group." (PMID 29081777, 2017).
pancreatic cancer (15 papers, 2014 to 2025). "Targeting the IRE1/XBP1 signaling axis represents a promising therapeutic strategy to counteract cancer-associated muscle wasting and potentially improve outcomes for patients with pancreatic cancer." (PMID 41249735, 2025). "The study identifies the IRE1α/XBP1 arm of the ER stress-induced unfolded protein response as a key driver of skeletal muscle wasting and demonstrates that its genetic or pharmacological inhibition can attenuate the loss of skeletal muscle mass and function during pancreatic cancer-induced cachexia." (PMID 41249735, 2025). "Collectively, these results suggest that the IRE1α/XBP1 signaling stimulates the activation of proteolytic systems in skeletal muscle during pancreatic cancer cachexia." (PMID 40655023, 2025). "To further understand the role of IRE1α/XBP1 axis in pancreatic cancer-induced cachexia, we utilized an in vitro model in which cultured myotubes were treated with KPC cells conditioned media (KPC-CM) for 24 h, followed by analysis of myotube diameter." (PMID 40655023, 2025). "Although our in vivo and in vitro results suggest that XBP1 is involved in the etiology of pancreatic cancer-induced cachexia, these genetic models reduce the levels of both unspliced and spliced XBP1." (PMID 40655023, 2025). "In summary, our present study provides initial evidence that IRE1α/XBP1 signaling mediates skeletal muscle wasting during pancreatic cancer-induced cachexia." (PMID 40655023, 2025). "To understand the mechanisms by which XBP1 promotes pancreatic cancer-induced muscle wasting, we performed bulk RNA-seq analysis of GA muscle isolated from Xbp1fl/fl and Xbp1mKO mice on day 21 after injection of PBS or KPC cells into the pancreas." (PMID 40655023, 2025). "Our results also demonstrate that genetic knockdown of STAT3 abrogates IXA4-induced reduction in myotube diameter, further suggesting that IRE1α/XBP1 signaling mediates muscle wasting during pancreatic cancer cachexia through the activation of STAT3 signaling." (PMID 40655023, 2025). "In the present study, we demonstrate that the IRE1α/XBP1 signaling axis is highly activated in skeletal muscle of the KPC mouse model of pancreatic cancer." (PMID 40655023, 2025). "Release of extracellular vesicles bearing tissue factor (EVTFs) from pancreatic cancer cells was inhibited by siRNA-mediated knockdown of IRE1α/XBP1 or PERK pathways." (PMID 37651191, 2023). "As for pancreatic cancer, the IRE1α-XBP1 signaling pathway has previously been shown to contribute to pancreatic cancer cell invasion in xenograft models." (PMID 34659567, 2021). "In pancreatic cancer, actors of the UPR are activated by gemcitabine and some of them, especially XBP-1 (X-box binding protein 1), are implicated in chemoresistance." (PMID 30441794, 2018). "We initially examined the ability of two IRE1α inhibitors (STF and HNA) to inhibit the splicing of XBP-1 to XBP-1s in pancreatic cancer cell lines." (PMID 24952679, 2014). "We next sought to investigate whether pharmacological inhibition of IRE1α/XBP1 signaling can attenuate pancreatic cancer-induced muscle wasting in mice." (PMID 40655023, 2025). "Collectively, our findings suggest that targeting IRE1α/XBP1 pathway may offer a therapeutic strategy to counteract muscle wasting during pancreatic cancer-induced cachexia." (PMID 41249735, 2025). "Our results using activators and inhibitors of IRE1α endonuclease activity suggest that IRE1α drives muscle wasting during pancreatic cancer cachexia mainly through promoting unconventional splicing of XBP1 mRNA which results in the production of transcriptionally active sXBP1 protein." (PMID 40655023, 2025). "Targeted ablation of XBP1 inhibits muscle wasting during pancreatic cancer cachexia." (PMID 40655023, 2025).
pancreatic cancer (continued). "Pancreatic cancer progression activates the IRE1/XBP1 signaling pathway in skeletal muscle." (PMID 41249735, 2025). "Altogether, our study highlights that the IRE1α/XBP1 signaling axis mediates pancreatic cancer-induced muscle wasting and inhibition of this pathway could be a potential approach to mitigate muscle wasting in pancreatic cancer patients." (PMID 40655023, 2025). "These genetic and pharmacological approaches suggest that blockade of IRE1α/XBP1 axis preserves skeletal muscle mass by suppressing the activation of UPS and autophagy in KPC model of pancreatic cancer cachexia." (PMID 40655023, 2025). "Both inhibitory molecules have proven to be effective against several pancreatic cancer and chronic lymphocytic leukemia (CLL) cell lines, wherein they inhibited the XBP1 splicing reaction in a dose-dependent manner." (PMID 33562589, 2021). "Three pancreatic cancer cell lines (MiaPaCa2, Panc0403, SU8686) were pre-treated with tunicamycin to induce ER stress resulting in IRE1α activation and splicing of XBP-1 to XBP-1s." (PMID 24952679, 2014). "In this study, we demonstrate that the IRE1α/XBP1 branch of the UPR promotes activation of the ubiquitin–proteasome system, autophagy, JAK-STAT3 signaling, and fatty acid metabolism in the skeletal muscle of the KPC mouse model of pancreatic cancer cachexia." (PMID 41249735, 2025). "Here, we demonstrate that the IRE1α/XBP1 arm of the UPR stimulates the activation of ubiquitin-proteasome system, autophagy, JAK-STAT3 signaling, and fatty acid metabolism in skeletal muscle of the KPC mouse model of pancreatic cancer cachexia." (PMID 40655023, 2025).
Huntington disease (13 papers, 2014 to 2023). Huntington disease (HD) is a rare neurodegenerative disorder of the central nervous system characterized by unwanted choreatic movements, behavioral and psychiatric disturbances and dementia. "For instance, we found that deletion of XBP1 in transgenic models of Huntington’s disease (HD) also leads to neuroprotection associated to autophagy induction, enhancing degradation of mutant huntingtin." (PMID 28725179, 2017). "Previously, we have uncovered a relevant role for XBP1 a conserved branch of the UPR in the progression of PD, and also for Huntington’s disease (HD), using a conditional knockout mouse model for XBP1 in the central nervous system." (PMID 38042807, 2023). "In some diseases as Huntington’s disease, spliced Xbp1 seems to have a deleterious effect and its absence leads to an improvement of the disease." (PMID 28437467, 2017). "Xbp1 deletion delays progression of Huntington's disease (HD) by increasing autophagy to degrade the mutant Huntingtin (Htt) protein." (PMID 28860159, 2017). "In this context, it is noteworthy that modulating XBP1 has proved efficient to protect against Huntington disease in mice model of this pathology." (PMID 27853315, 2016). "For example, downregulation of PERK is protective in some ALS (amyotrophic lateral sclerosis) or prion disease models, whereas increased Xbp1 can be protective in Parkinson’s and Huntington’s disease models." (PMID 27524482, 2016). "Finally, a polymorphism in the Xbp1 promoter is one of the risk factors for Alzheimer’s disease and the pathobiology of protein aggregation conditions such as Alzheimer’s and Huntington’s disease can be regulated via a modulation of the IRE1ɑ-XBP1 branch of the UPR." (PMID 31260448, 2019). "It is therefore not surprising that the XBP1 branch of the UPR pathway has been implicated in many protein aggregation diseases including Alzheimers, Huntington’s disease, type II diabetes and several skeletal conditions amongst others." (PMID 31260448, 2019). "Conditional deletion of XBP1 in the central nervous system (CNS) provides protective effects through upregulation of autophagy levels, improving motor performance in ALS, PD and Huntington's disease models, whereas XBP1 deficiency does not affect Prion pathogenesis in vivo." (PMID 30450103, 2018). "Interestingly in this study, XBP-1 implication in Huntington’s disease seems to be independent of its function in ER stress regulation." (PMID 25216759, 2014).
ZIKV infection (12 papers, 2017 to 2025). "Spliced XBP1 has been described to cause ER expansion and remodeling and we find that ER redistribution during ZIKV infection requires IRE1α nuclease activity." (PMID 32138181, 2020). "As expected, treatment with STF inhibited the splicing of XBP1 mRNA induced by ZIKV infection while treatment with IXA4 boosted XBP1 splicing in ZIKV infected cells." (PMID 41157563, 2025). "There was a trend towards increase in spliced XBP1/GAPDH in palmitate treated cells compared to ZIKV infection alone." (PMID 34200091, 2021). "We earlier demonstrated that ZIKV infection of trophoblasts induces an increase in the levels of C/EBP homologous protein (CHOP) mRNA and Spliced X box associated protein-1 (XBP1) mRNA, which are key markers of ER stress." (PMID 34200091, 2021). "Although XBP1 targets are not induced in response to HCV and WNV, we found that ZIKV infection does induce the XBP1 targets ERDJ4 and P58IPK." (PMID 32138181, 2020). "Together, these results suggest that ZIKV infection activates IRE1α to splice XBP1 mRNA, leading to upregulation of XBP1 targets." (PMID 32138181, 2020). "We further found that genetic disruption of IRE1α and XBP1 limits ZIKV infection in multiple tissues in vivo in an adult murine infection model." (PMID 32138181, 2020). "Our study compared the HCAR2 mRNA levels in the context of ZIKV infection with treatment of IRE1 inhibitors or XBP1-specific shRNAs." (PMID 32039055, 2019). "The ratios of xbp1s/t-xbp1 between mock and ZIKV infection were 15.8-fold (24 hpi) and 32.6-fold (48 hpi) in CCF-STTG1 cells, and 3.1-fold (24 hpi) and 10.9-fold (48 hpi) in SK-N-SH cells." (PMID 30241539, 2018). "The results indicated that the expression of phospho-IRE1 and XBP1 significantly increased in the cerebellum and mesocephalon during ZIKV infection." (PMID 30241539, 2018). "In SVG-A cells, ZIKV infection stimulates the expression of BiP and XBP1 that activate major arms of the UPR." (PMID 29036922, 2017). "We observed increased apoptosis in placental trophoblasts with ZIKV infection along with increased XBP1 splicing and IRE1α activation suggests that the mechanism of ZIKV-induced apoptosis could be due to the sustained ER stress." (PMID 33500388, 2021). "The results showed that ZIKV infection induced IRE1 mediated XBP1 splicing." (PMID 33432092, 2021). "Here, we examined the role of the IRE1α-XBP1 branch of the UPR in ZIKV infection." (PMID 32138181, 2020). "To determine whether IRE1α promotes ZIKV infection via XBP1 splicing and activation, we targeted XBP1 for genetic inactivation using CRISPR-Cas9." (PMID 32138181, 2020). "ZIKV infection has been shown to promote XBP1 splicing and XBP1s translocation into the nucleus, leading to elevated expression of XBP1 downstream effectors such as ER degradation-enhancing α-mannosidase-like 1 (EDEM-1) and CHOP, indicating the activation of the IRE1 arm of the UPR." (PMID 31959174, 2020). "We find that ZIKV infection induces XBP1 mRNA splicing and induction of XBP1 target genes." (PMID 32138181, 2020). "We also found that specific XBP1 target genes are upregulated during ZIKV infection." (PMID 32138181, 2020). "Together, our data indicate that the ER stress response component IRE1α promotes ZIKV infection via XBP1 and may represent a potential therapeutic target." (PMID 32138181, 2020). "Consistent with this idea, induction of ER stress and the IRE1/XBP1 axis by treatment with tunicamycin (Tn) revealed both a potent splicing of the XBP1 mRNA and the induction of Erdj4 and Edem1 transcripts; thus, confirming a partial activation of XBP1s during ZIKV infection." (PMID 41157563, 2025). "However, treatment of palmitate did not prevent the increased levels of spliced XBP1 caused due to ZIKV infection." (PMID 34200091, 2021). "However, knockout of ERAD genes had minimal effect on ZIKV infection, suggesting that other XBP1 targets may promote ZIKV infection." (PMID 32138181, 2020).
ZIKV infection (continued). "In this study, we examined the role of IRE1α in ZIKV infection and found that IRE1α promotes ZIKV replication via XBP1 in cultured cells." (PMID 32138181, 2020). "Previous studies have reported that in response to ZIKV infection, phosphorylated IRE1 splices a 26-nucleotide intron from full-length XBP1 mRNA (XBP1u), resulting in the splicing XBP1 form (XBP1s)." (PMID 32039055, 2019). "Collectively, the findings demonstrated that ZIKV infection in the nervous tissues of the mouse brain activated phospho-IRE1 and induced the post-transcriptional cleavage of xbp1." (PMID 30241539, 2018). "As ZIKV infection did not induce XBP1 splicing, transcription initiation at ERSE or UPRE motifs, or expression of ER stress response genes XBP1 is unlikely to be responsible for the observed induction of lipid metabolism genes in response to ZIKV infection." (PMID 36097162, 2022). "ZIKV infection did not alter XBP1 splicing in moDCs, while treatment with the ER stress inducer tunicamycin increased and decreased sXBP1 and uXBP1 mRNA levels, respectively, as expected (, d)." (PMID 36097162, 2022). "Similarly, the mRNA level of HCAR2 in XBP1-KD cells was not enhanced in response to ZIKV infection." (PMID 32039055, 2019). "Results show that the spliced XBP1 message was observed in ZIKV infected cells, while no splicing of XBP1 was seen in control (mock) infections, showing induction of the UPR in response to ZIKV infection." (PMID 33432092, 2021).